BRCA1 (BRCA1 DNA repair associated)
Diseases named in the same sentence as BRCA1 in open-access papers (continued):
Sharing a sentence is not in itself a finding about the gene and the disease.
breast cancer (continued). "This study highlights the frequent promoter methylation of BRCA1 and its prognostic significance, irrespective of BRCA1 gene mutation in Egyptian patients with early-stage breast cancer." (PMID 27413552, 2016). "In breast cancer, ANXA1 expression is associated with BRCA1/2 mutations." (PMID 27941907, 2016). "Unfortunately, no drugs are on the market or under trial that target BRCA1 mutations in breast cancer patients." (PMID 27801815, 2016). "Furthermore, it was shown, that serum levels of RANKL and its decoy receptor OPG are deregulated in BRCA1-mutation carriers, lower OPG serum levels being associated with an increased risk of breast cancer." (PMID 27881737, 2016). "From a strictly genetic perspective, if genetic instability caused by loss of BRCA1 allows the acquisition of mutations in critical checkpoint genes during puberty, this phenomenon would enable rare BRCA1 null cells to escape death and proliferate, leading to early breast cancer onset." (PMID 27259235, 2016). "Four recurrent BRCA1 mutations (c.3780_3781delAG, c.5154G > A, c.5468-1del8 and c.5470_5477del8) and two recurrent BRCA2 mutations (c.3109C > T and c.5682C > G) were identified in unrelated breast cancer patients." (PMID 26852015, 2016). "Triple-negative breast cancer patients carrying founder BRCA1 mutations were likely to had a decreased risk of distant recurrence and breast cancer-specific mortality compared to BRCA1 non-carriers." (PMID 27257965, 2016). "Since high pCR is suggestive of greater recurrence-free survival, this data suggests that platinum-based agents may be an effective neoadjuvant chemotherapeutic option for women with BRCA-1 positive breast cancer." (PMID 26873719, 2016). "A recent study used targeted sequencing of mitochondrial DNA in high-risk breast cancer patients negative for BRCA1/2 mutations to provide new clinical evidence for MT-CYB variants as a risk factor for hereditary breast cancers." (PMID 27136895, 2016). "PARP inhibitor biomarkers, such as olaparib for patients with BRCA1/2-mutant tumors, ovarian, and colorectal cancers; iniparib for breast and lung cancers; rucaparib for breast and ovarian cancer; and veliparib for melanoma and breast cancer, are used." (PMID 26973813, 2016). "As a first step to evaluate clinical relevance, we analyzed protein expression of topoisomerase I (TOP1) and P-cadherin (CDH3) in a large panel of breast cancer tissues from BRCA1/2 mutation carriers and women without a hereditary predisposition." (PMID 27566577, 2016). "In addition, the synergistic results are consistent with and expand on recent observations of the effect of combining PI3K/mTOR and PARP inhibitors in the treatment of BRCA1-related breast cancer." (PMID 27553366, 2016). "At PARPinhibitory concentration, 7-methylguanine itself was not cytotoxic but able tosensitize BRCA1-deficient breast cancer cells to commonly used chemotherapeuticagents (cisplatin and doxorubicin)." (PMID 27437145, 2016). "The combination of a PI3K inhibitor BKM120 with PARP inhibitor Olaparib has reported to exhibit synergistic therapeutic effects for the treatment of a genetic mouse model of BRCA1-related breast cancers as well as for the treatment of BRCA1-proficient triple negative breast cancers." (PMID 26909613, 2016). "The contribution of BRCA1/2 mutations to both hereditary and sporadic breast cancer has not yet been thoroughly investigated in Algeria." (PMID 26997744, 2016). "We and others have reported that the breast cancer risk fraction contributed by missense variants in BRCA1, BRCA2, ATM and CHEK2 is as high, if not higher, than protein-truncating variants in these genes." (PMID 27099641, 2016).
breast cancer (continued). "BRCA1 cytoplamic accumulation in breast cancer cells plays an important role in apoptosis." (PMID 27494651, 2016). "We also predicted that breast cancer would occur in 41 women (range 36–62) incorrectly identified with no pathogenic mutations and in 12,460 women without BRCA1 or BRCA2 mutations." (PMID 27252788, 2016). "This suggests that low levels of EZH2 are necessary to regulate normal mammary epithelial cell proliferation; however, EZH2 overexpression in ER-negative MDA-MB-231 cells results in decreased BRCA1 and uncontrolled proliferation which contributes to tumorigenesis of breast carcinoma." (PMID 27113214, 2016). "Similar to TOP1, increased CHD3 expression was associated with BRCA1/2-related breast carcinoma, independent of TNBC and age." (PMID 27566577, 2016). "We demonstrated increased CDH3 levels in a large panel of human BRCA1-related breast carcinomas." (PMID 27566577, 2016). "It has been suggested that the expression of BRCA1/2 might also be related with chemoresistance and shorter survival of patients with breast carcinoma and ovarian carcinoma." (PMID 27643881, 2016). "We demonstrated that BRCA1-deficient secretome proteins could cluster most human BRCA1- and BRCA2-related breast carcinomas at the transcriptome level." (PMID 27566577, 2016). "BRCA1 loss in Cal51 (breast carcinoma) and OVCAR5 (ovarian carcinoma) cells did neither impair their viability, nor affected cell cycle progression." (PMID 27845331, 2016). "Topoisomerase I (TOP1) and P-cadherin (CDH3) expression was investigated by immunohistochemistry on tissue microarrays of a large panel of 253 human breast carcinomas with and without BRCA1/2 mutations." (PMID 27566577, 2016). "Nonetheless, since the majority of breast cancer cases with BRCA1 or BECN1 copy number alteration contain concurrent deletions of both BRCA1 and BECN1, it is difficult to use copy number alterations as a parameter for distinguishing the effects of these two genes in breast cancer." (PMID 25825707, 2015). "Estimated ORs for the association of the FokI and BsmI SNPs with breast cancer in BRCA1/2 non-carriers by family history and menopausal status (complete and reduced covariate model)." (PMID 26517870, 2015). "Germline mutations BRCA1 and BRCA2 explain around 20% of familial breast cancer." (PMID 26426992, 2015). "Further studies to observe whether a specific BRCA1-related sporadic breast cancer can indicate a favorable prognosis would be beneficial." (PMID 25789047, 2015). "While the HMMR association study in BRCA1/2 mutation carriers drew on a partial dataset from the Consortium of Investigators of Modifiers of BRCA1/2 (CIMBA), the depicted mechanistic model highlighted additional gene candidates for breast cancer risk; i.e., AURKA, TPX2, and TUBG1." (PMID 25830658, 2015). "Since MCF7 is a luminal cell line and MDA-MB-231 a triple-negative cell line, our data can potentially reveal whether the miRNAs tested may have a different effect on BRCA1 in these two subtypes of breast cancer." (PMID 26392359, 2015). "There is no demonstrated benefit for primary chemoprevention of breast cancer in BRCA1 or BRCA2 mutation carriers (I,A)." (PMID 26669313, 2015). "In particular, due to the human-like life span of pigs, a porcine model of BRCA1 driven breast cancer could allow the testing of long term preventative measures, as well as strategies to counter the persistence of minimal residual disease after treatment." (PMID 26379698, 2015).
breast cancer (continued). "SPT5 was also confirmed as a relevant target of BRCA1 interaction in breast cancer." (PMID 26418880, 2015). "BRCA1 genetic testing was performed after the first breast cancer." (PMID 25880076, 2015). "Here, we found that the association of the b allele of the BsmI with breast cancer risk was further increased in BRCA1/2 non-carriers who reported a positive family history of breast and/or ovarian cancer." (PMID 26517870, 2015). "(2008) studied postmenopausal women who carried a BRCA1 mutation to compare the risks of breast cancer among those who used HRT and those who did not." (PMID 26557407, 2015). "The genetic background in families with hereditary breast cancer without predisposing germ line mutations in BRCA1 and BRCA2 (non-BRCA families) is still to a large extent unclear even though progress has been made." (PMID 26082817, 2015). "Eligible publications were observational studies assessing the survival of breast cancer patients carrying a BRCA1/2 mutation compared to non-carriers or the general breast cancer population." (PMID 25816289, 2015). "In breast cancer, however, hypermethylation is often found in BRCA1." (PMID 25908947, 2015). "Although paclitaxel-mediated increases in the expression of some oncogenes have been previously reported in both human patients with breast cancer and experimental breast cancer models, this is the first study that analyzed co-expression of BRCA1-IRIS and ErbB family members." (PMID 25583261, 2015). "In sporadic breast cancers, germline BRCA1 mutations are not detected, but somatic inactivation of the BRCA1 gene by DNA hypermethylation has been reported to occur as an epigenetic event." (PMID 26124080, 2015). "However, BRCA1 and BRCA2 germline mutations are present in only half of all families with a strong family history of breast cancer." (PMID 25927356, 2015). "A functional link between BRCA1 and miRNAs has been recently observed but very little is known about miRNAs involvement in familial breast cancer with and without BRCA mutations." (PMID 25333258, 2015). "In a recent study it was hypothesized that BRCA1 may down-regulate the expression of the EGFR gene by increasing the miR-146a level in breast cancer-derived cells." (PMID 26392359, 2015). "In the present study, a case–control GWA study for breast cancer risk was carried out in a large collection of Sardinian breast cancer patients negative for BRCA1 or BRCA2 mutations." (PMID 25956309, 2015). "The study reported a 62% reduction in breast cancer with prophylactic tamoxifen in healthy BRCA2-mutation carriers, but there was no reduction in breast cancer incidence among women with an inherited BRCA1 mutation." (PMID 26557407, 2015). "All tumours were derived from Caucasian patients diagnosed with breast cancer lacking any known germ-line mutations in BRCA1 or BRCA2." (PMID 26300993, 2015). "Significance: Up-regulation of BRCA1 by dietary and/or pharmacological interventions may have significant implications for the prevention and perhaps therapy of sporadic breast cancer." (PMID 25762631, 2015). "About 51% of the students with a family history of breast cancer and 20% with no family history of breast cancer had BRCA1 and BRCA2 mutations." (PMID 25641872, 2015). "The study findings suggest that BRCA1 mutations are not a substantial cause of breast cancer in familial pancreatic cancer kinships as none of the participants were found to possess a BRCA1 mutation from DNA sequencing." (PMID 26236408, 2015). "In this study, we aimed to find novel breast cancer susceptibility genes by whole-exome sequencing in nine early-onset familial breast cancer patients without BRCA1/2 mutations." (PMID 25945795, 2015). "It has been detected in 5% of breast cancer patients from non-BRCA1 and BRCA2 families." (PMID 25674498, 2015).
breast cancer (continued). "The original study suggested an association between the rs299290 risk allele and ERα-negative breast cancer for BRCA1 mutation carriers." (PMID 25830658, 2015). "Quantitative measures of BPE and FGT are different before and after RRSO, and their relative changes are associated with prediction of developing breast cancer, potentially indicative of women who are more susceptible to develop breast cancer after RRSO in BRCA1/2 mutation carriers." (PMID 25986460, 2015). "miR-335 also suppresses neuroblastoma cell invasiveness by targeting multiple genes encoding mediators in the TGF-pathway, and it is involved in the regulation of BRCA1 in breast cancer and is silenced through genetic and epigenetic mechanisms in metastatic breast cancer cells." (PMID 26214687, 2015). "Building upon the previously established roles of BRCA1 and PIG3 in breast cancer, our results provide the first explanation of an important mechanism for BRCA1 to positively regulate the expression of PIG3 and influence the progression of breast carcinoma cells." (PMID 25797244, 2015). "This work establishes the first porcine model system for studying BRCA1 and breast cancer." (PMID 26379698, 2015). "While recognized as a critical player in breast cancer risk and behavior, no approaches have been developed to enhance BRCA1 function in breast cancer to improve patient outcome." (PMID 25970777, 2015). "Similarly, bioinformatic analysis of methylation levels in the HumanMethylation450 TCGA database revealed insignificant differences between breast cancer and adjacent tissue for the BRCA1 promoter region that we examined." (PMID 26510686, 2015). "Although the BRCA1 mutation is related to triple negative breast cancer, a family history of breast cancer did not influence hormonal sensitivity in this study, as three of five cases in the Younger than 30 group were PgR-positive." (PMID 26207196, 2015). "Interestingly, one study demonstrated that women with BRCA1 and BRCA2 mutations have greater susceptibility to breast cancer, but also higher fertility." (PMID 26056364, 2015). "In a previous study from our group, we used multiplexed PCR-based genotyping technology and showed that the frequency of selected BRCA1 mutations was moderate in familial and high in nonfamilial breast cancers." (PMID 25948282, 2015). "We propose that the decreased expression of BECN1 (another tumor suppressor gene located near BRCA1) in sporadic basal-like breast tumors may partly explain the phenotypic overlap of this disease with hereditary BRCA1 breast cancer." (PMID 25825707, 2015). "It was recently shown that haplogroup H was more frequent in BRCA2 carriers whereas haplogroup X was more frequent in BRCA1 carriers compared to patients not carrying BRCA mutations among Italian familial breast cancer cases." (PMID 25783644, 2015). "ANXA8 has been reported to be up-regulated in BRCA1-related breast cancer and PDAC." (PMID 26318045, 2015). "In this study, we screened the mutations on the entire coding sequence of the CHEK2 gene by direct sequencing on a cohort of Asian high-risk breast cancer patients who have been tested negative for BRCA1 and BRCA2 gene mutations." (PMID 25629968, 2015). "Similar levels of accuracy were attained for women who carried a BRCA1/2 mutation as for women with a family history of breast cancer but with no known BRCA1/2 mutation (termed BRCAX)." (PMID 26538066, 2015). "The main focus of this study was to analyze the relationship between high ANXA1 tumor expression with BRCA1/2 germline carriership and survival in breast cancer patients, including those with specific tumor subtypes, using a large dataset of pooled breast cancer series." (PMID 26137966, 2015). "We profiled peripheral blood mononuclear cells from women with a family history of breast cancer (with or without a germline BRCA1/2 variant) and from controls." (PMID 26538066, 2015).
breast cancer (continued). "Surprisingly, TRs demonstrated prognostic significance only in those patients diagnosed for a BRCA1 germline mutation but not in sporadic breast cancer cases." (PMID 26029931, 2015). "We have conducted such a case–control GWA study for breast cancer risk in our collection of Sardinian breast cancer patients who are negative for BRCA1 or BRCA2 mutations." (PMID 25956309, 2015). "PARP1 inhibitors are used to treat breast cancer exhibiting deletion of BRCA1 or BRCA2." (PMID 25872931, 2015). "We screened the entire coding region of CHEK2 gene on 59 high-risk breast cancer patients who tested negative for BRCA1/2 germline mutations from UKM Medical Centre (UKMMC), Hospital Kuala Lumpur (HKL) and Hospital Putrajaya (HPJ)." (PMID 25629968, 2015). "Knockdown of BRCA1 resulted in the downregulation of FOXA1 expression and enhancement of FOXA1 promoter methylation in MCF-7 breast cancer cells, whereas the reconstitution of BRCA1 in Brca1-deficent mouse mammary epithelial cells (MMECs) promoted Foxa1 expression and methylation." (PMID 25531315, 2015). "While a number of studies have examined miRNA profiles across the molecular subtypes of breast cancer, it is unclear whether BRCA1 basal-like cancers have a specific miRNA profile." (PMID 26152113, 2015). "High breast cancer risk in BRCA-mutation carriers is particularly evident premenopausally (relative risk 32 and 10 for 40–49-year-old BRCA1/2-mutation carriers, respectively), whilst removal of both ovaries in premenopausal BRCA1/2-mutation carriers markedly reduces breast cancer risk." (PMID 26629528, 2015). "It is therefore unlikely that mutations in the mitochondrial genome have the potential to explain a high proportion of the excess of breast cancer risk of women with a familial history but without BRCA1/2 mutations." (PMID 26406445, 2015). "BRCA-1 protein levels were reduced by an additional ~40 % in DMBA-induced mammary tumors." (PMID 26715507, 2015). "In line with this hypothesis, talazoparib will be tested in BRCA1/2 wild type breast cancer with high HRD score or deleterious germline or somatic mutation implicated in the HR pathway." (PMID 26268938, 2015). "Survival perspectives of BRCA1/2 mutation carriers diagnosed with breast cancer are unclear and current evidence does not support differential treatment decisions (apart from the use of PARP inhibitors)." (PMID 25816289, 2015). "Intriguingly, the same HMMR variation as originally detected in the Ashkenazi Jewish population was suggested to be associated with breast cancer risk in BRCA1, but not in BRCA2 mutation carriers." (PMID 25830658, 2015). "Importantly, feeding a diet rich in fish oil to mice bearing human breast cancer xenografts strongly induced expression of BRCA1 mRNA and protein in the tumors." (PMID 25762631, 2015). "Nevertheless, the combined frequency of BRCA1 and BRCA2 mutations in the general populations is nearly 0.5%; thus, more common variants are more relevant for determining predisposition to breast cancer." (PMID 25339628, 2015). "A large fraction of these susceptibility alleles are associated with increased risk in persons with a family history of breast cancer despite the absence of mutations in BRCA1 or BRCA2, accounting for about 30 % of the familial risk of the disease." (PMID 25956309, 2015). "The mutation frequency was higher in the subgroup of TNBC than in the premenopausal breast cancer patients: 23.3 % (7/30) of TNBC patients harbour a pathogenic mutation in either BRCA1 or BRCA2, compared to 12.0 % (11/92) of all premenopausal breast cancer patients." (PMID 26577449, 2015). "Thus, BRCA1 can contribute to the metastasis of breast cancer by influencing the expression of CSF2." (PMID 26039571, 2015). "On the another hand, a growing number of studies have demonstrated loss of heterozygosity and a reduced level or absence of BRCA1 expression in sporadic breast cancer." (PMID 25789047, 2015).